EPHA2 (EPH receptor A2)
Diseases named in the same sentence as EPHA2 in open-access papers (continued):
Sharing a sentence is not in itself a finding about the gene and the disease.
ovarian carcinoma (continued). "EPH receptor A2, one of miR-200a targets, promotes tumor growth and predicts poor prognosis for ovarian cancer patients." (PMID 30095616, 2018). "In ovarian cancers, anti-EphA2-siRNA with DOPC reduced the 35–50% of tumor volume and its antitumor activity was increased when it has given with anticancer drug paclitaxel (67–82%)." (PMID 29861465, 2018). "We proved that combined inhibition of EphA2, an ovarian cancer oncogene, with EphA2 siRNA and miR‐520d‐3p mimic exhibits synergistic effects." (PMID 29024380, 2017). "sEVs secreted from DXR-induced senescent RPE-1 cells also promoted the growth of OVK-18 cells (human ovarian cancer cell line) and T.T cells (human oesophageal cancer cell line) in an EphA2-dependent manner." (PMID 28585531, 2017). "In this study, miR‐520d‐3p was shown to directly target EphA2 and EphB2 and inhibit their protein expression in ovarian cancer cells." (PMID 29024380, 2017). "Previously, we showed that EphA2-siRNA delivered by multistage vectors (MSV-EphA2) accumulated in tumor tissues and induced apoptosis in ovarian cancer cells." (PMID 25788424, 2015). "We confirmed that the expression level of MMP-9 is correlated with the regulation of EphA2 during treatment for the ovarian cancer." (PMID 25788424, 2015). "EphA2 overexpression in the majority of ovarian cancer patients predicts poor clinical outcome connected to shorter overall survival." (PMID 25906164, 2015). "Historically, EphA2 was considered a potential therapeutic target for the treatment of ovarian cancer via RNA interference." (PMID 25788424, 2015). "DOPC-encapsulated siRNA targeting the oncoprotein EphA2 was highly effective in reducing EphA2 expression 48 h after administration of a single dose in an orthotopic model of ovarian carcinoma." (PMID 23844368, 2013). "EphA2 is a tyrosine-kinase receptor of 130KDa, belonging to Eph family; EphA2 is over-expressed in many cancers, including ovarian cancer, in which its expression is related to more aggressive cancer behaviour." (PMID 19384429, 2007). "Moreover, in ovarian cancer, RSK-mediated phosphorylation of EphA2 was associated with intrinsic and acquired chemoresistance to cisplatin and carboplatin." (PMID 39596256, 2024). "Furthermore, in vivo delivery of EphA2 siRNA using nanoliposomal in ovarian cancer has demonstrated effective targeting of cancer cell and remarkable anticancer effects." (PMID 38811954, 2024). "Interestingly, previous studies revealed that the high expression of ABCA1, APLP2, C3, EPHA2, and EFNA1 were associated with poor prognosis and epithelial ovarian cancer progression." (PMID 39135097, 2024). "EphA2 expression levels significantly correlated with clinical stage of colon adenocarcinoma and testicular germ cell tumors, where EphA2 levels increased in advanced clinical stages, while in kidney renal cell carcinoma and ovarian carcinoma, EphA2 expression decreased." (PMID 39596256, 2024). "In addition, EphA2 is overexpressed in various cancers, including breast cancer, esophageal cancer, melanoma, lung cancer, prostate cancer, ovarian cancer, and endometrial cancer." (PMID 36835335, 2023). "In ovarian cancer, higher EPHA2 expression corresponds to more aggressive tumors." (PMID 33834064, 2021). "Other studies showed the interaction between miR‐520d and EphA2 could enhance tumour suppression in ovarian cancer and gastric cancer." (PMID 32233022, 2020). "Interestingly, high expression of VE-cadherin and EphA2 has been found in clinical samples from ovarian cancer patients that exhibit a highly invasive phenotype." (PMID 31612116, 2019). "Moreover, in vivo therapeutic delivery of miR‐520d‐3p mimic and EphA2 siRNA induced potent synergy, resulting in substantial inhibition of tumor growth when compared with individual treatments in ovarian cancer tumor xenograft models." (PMID 29024380, 2017). "It was also observed that abnormal expression of EphA2 could lead to survival of patients with ovarian cancer." (PMID 25803614, 2015).
ovarian carcinoma (continued). "In an orthotopic mouse model of ovarian cancer the oncogene EphA2 could be silenced after three weeks of treatment with EphA2-targeting siRNA-DOPC and the tumor growth was reduced." (PMID 24276320, 2013). "Here, we explore the therapeutic potential of dasatinib, a small-molecule inhibitor that targets multiple cytosolic and membrane-bound tyrosine kinases, including members of the Src kinase family, EphA2, and focal adhesion kinase for the treatment of ovarian cancer." (PMID 19861960, 2009). "EphA1 and EphA2 over-expression was correlated with ephrin A1 suggesting that their interaction may have a role in ovarian cancer progression." (PMID 16737551, 2006). "Our findings of a strong EphA2 upregulation in primary fallopian tube epithelial cells suggests that targeting EphA2 and probably other Eph receptors or its co-receptors could offer a tool to control Chlamydia-induced ovarian cancer." (PMID 25906164, 2015). "Interestingly,the EphA2 gene is located on chromosome 1p36.1, whichis not only a genetic “hot spot” in cancer, but also thesecond most common site of complex karyotypic abnormalitiesin ovarian cancer." (PMID 19384429, 2007). "In ovarian cancers, OPCML drives inactivation and degradation of the RTKs HER2, HER4, FGFR1, FGFR3, EPHA2, and AXL, and the specificity of this network is underscored by identification of a group of RTKs that are unaffected by OPCML." (PMID 40699804, 2025). "EPHA2, the most extensively studied EPH in ovarian cancer, exhibited overexpression both in ovarian carcinoma cell lines and patient tissue samples, while EPHB4 was found to be upregulated in endometrial cancer in a series of studies." (PMID 35328669, 2022). "Only 3 of 10 MPAS genes (PHLDA1, DUSP4, and EPHA2) reflect MEK/ERK pathway activity significantly and consistently across multiple experimental models and clinical tissue samples of ovarian cancer." (PMID 36362153, 2022). "For example, they found low levels of certain markers that have been gaining traction as drug targets (EphA2), or that have been touted as specific for (MUC16 and FOLR1) or overabundant (Mesothelin) in ovarian cancer." (PMID 30011875, 2018). "We performed two co-cultured CRISPR screens in the ovarian cancer cell line OVCAR-8, using two distinct CAR-THP-1 cell lines: liquid tumor relevant CD19-targeting CAR-THP-1, and solid tumor relevant EphA2-targeting CAR-THP-1." (PMID 40595560, 2025). "In ovarian cancer, a previous study indicated that miR-200 family members might affect the β-tubulin III protein and negatively regulate EphA2 expression." (PMID 36091129, 2022). "In fact, in ovarian cancer cells VEGF-A may up-regulate most of the signaling molecules in the VE-cadherin signaling cascade: VE-cadherin itself, Epithelial cell kinase (EphA2) and MMP-2." (PMID 28320399, 2017). "We established a mouse model for ovarian cancer development and treatment by orthotopic implantation of the human drug-resistant ovarian cancer cell line HeyA8-MDR, followed by porous silicon particle- or multistage vector (MSV) - enabled EphA2 siRNA therapy." (PMID 25788424, 2015). "In the present study, EphA2 was found to modulate the sensitivity of NPC cells to paclitaxel, which was consistent with previous studies that have reported that EphA2 inhibition leads to increased paclitaxel sensitivity in ovarian cancer." (PMID 25351620, 2015). "To further establish the efficacy and specificity of this targeting method, we established a model using ovarian cancer cell lines either positive or negative for expression of EphA2 and positive for expression of EGFR." (PMID 20064265, 2010). "Likewise, in PEO1 ovarian cancer cells, PTEN knockdown activated Src kinase and increased EphA2 expression, whereas inhibiting Src with dasatinib potently suppressed Src phosphorylation and reduced EphA2 expression." (PMID 41130297, 2025).
ovarian carcinoma (continued). "We have previously demonstrated that delivery of EphA2 siRNA through 1,2-dioleoyl-sn-glycero-3-phosphatidylcholine (DOPC) neutral liposome nanoparticles (EPHARNA) showed highly efficient in vivo delivery to the tumor, resulting in decreased tumor burden in mouse ovarian cancer models." (PMID 36835335, 2023). "Several genes found in our analysis have previously been described as biomarkers of ovarian cancer or potential therapeutic targets, including genes from the ITGA and ITGB superfamily, laminins, fibroblast growth factors, collagens, insulin growth factors, EGFR, FN1, EPHA2, TNC, SPP1, and VTN." (PMID 36352420, 2022). "For the more demanding in vivo application the nanoliposomal EphA2-targeted therapeutic EPHARNA (1,2-dioleoyl-sn-glycero-3-phosphatidylcholine; DOPC) was developed, leading to efficient reduction in EphA2 expression and tumor growth in an ovarian cancer mouse xenograft model." (PMID 33572758, 2021). "There are many cancers and cancer cell lines that overexpress both EPHA2 and EFNA1, including bladder and ovarian cancer, which indicates that EFNA1 expression does not always lead to EPHA2 downregulation." (PMID 20979646, 2010).
pancreatic cancer (58 papers, 2008 to 2025). "Our findings, overall, align with a study that demonstrated tumor cell-intrinsic EphA2 inhibits anti-tumor immunity in pancreatic cancer through the regulation of PTGS2, the gene encoding cyclooxygenase-2 (COX2)." (PMID 40867322, 2025). "Serum exosomal EphA2 protein is highly expressed in pancreatic cancer patients and is associated with poor prognosis." (PMID 40538442, 2025). "EphA2 was shown to have the highest expression level among Ephs in pancreatic tumours, and its expression correlated with a loss of T-cell infiltration." (PMID 36830852, 2023). "This technique was also reported to distinguish pancreatic cancer patients from healthy subjects via detection of an EV marker, ephrin type-A receptor 2 (EphA2), associated with pancreatic cancer for clinical diagnosis and prognosis." (PMID 34374936, 2022). "Our findings imply that EphA2 is a novel tumor suppressor in pancreatic cancer, with the loss of function promoting rapid development of premalignant lesions." (PMID 33891893, 2021). "EphA2 is overexpressed in a number of human cancers, including pancreatic cancer, and this is associated with poor prognosis." (PMID 18797457, 2008). "TheEphA2-EV nPES assay demonstrated high diagnostic accuracy, effectivelydistinguishing pancreatic cancer from pancreatitis and healthy controls.Furthermore, EphA2-EV levels correlated with tumor progression andearly treatment responses, outperforming conventional ELISA." (PMID 40720603, 2025). "Additionally, high level of exo-EphA2 expression in pancreatic cancer is linked to a shorter overall survival." (PMID 39113699, 2024). "EphA2 overexpression has been observed in pancreatic cancer and associated with poor prognosis." (PMID 33546207, 2021). "Therefore, serum EphA2-NF could be used to detect a high-risk case of pancreatic cancer development from IPMN." (PMID 37712876, 2023). "In pancreatic cancer, EphA2 expression is dramatically inversely correlated with survival, and the detection of EphA2 fragments in plasma has been recently proposed as a new possible diagnostic approach to anticipate the aggressiveness of pancreatic cancer in patients." (PMID 32397624, 2020). "While one prior study demonstrated that tumor-intrinsic EphA2 can inhibit anti-tumor immunity in pancreatic cancer, its effect on the tumor immune microenvironment has been largely unexplored." (PMID 40867322, 2025). "This approach enabled the detection of the expression of two pancreatic cancer biomarkers, live erythropoietin-producing hepatocellular A 2 (EphA2), and epithelial cell adhesion molecule (EpCAM)." (PMID 40284444, 2025). "In pancreatic cancer, EphA2 contributes to tumour vascularisation by enhancing endothelial sprouting and tube formation." (PMID 41294859, 2025). "First, [225Ac]AJ210 selectively binds to EphA2-expressing pancreatic tumors, delivering alpha-particle radiation with high LET." (PMID 40225586, 2025). "The median expression of the EphA2 gene was particularly high in pancreatic cancer compared to other cancer types." (PMID 40225586, 2025). "An analysis of genomic data from the Cancer Cell Line Encyclopedia (CCLE) revealed variable expression of the EphA2 gene across different human cancer cell lines, with pancreatic cancer cells showing higher expression levels compared to others." (PMID 40225586, 2025). "Another 2017 report identified ephrin type-A receptor 2 (EphA2) as a candidate biomarker for pancreatic cancer." (PMID 39001524, 2024). "This study aims to enroll 18 patients with advanced solid tumors, including pancreatic cancer, who exhibit positive expression of EphA2 and have experienced disease progression after at least one line of standard therapy." (PMID 39417449, 2024). "In pancreatic cancer cell lines, the dimeric agents induced EphA2 phosphorylation, internalization, and degradation." (PMID 39417449, 2024).
pancreatic cancer (continued). "The EPH receptor A2 (EphA2), a member of the Eph receptor family, is significantly overexpressed in pancreatic cancer tissues." (PMID 39417449, 2024). "The mean values for serum EphA2-NF in the validation cohort were 75.6 pg/mL for pancreatic cancer cases (n = 472), 46.9 pg/mL for IPMN (n = 16), and 46.6 pg/mL for PNET (n = 19)." (PMID 37712876, 2023). "To determine the clinical utility of serum EphA2-NF for pancreatic cancer diagnosis, we first measured its concentration using CLIA in 299 serum samples in the test cohort." (PMID 37712876, 2023). "In pancreatic cancer, EphA2 activity on tumour cells regulated immunological suppression by excluding T-cells." (PMID 36830852, 2023). "We also performed univariate Cox regression analyses to identify prognostic factors for patients with pancreatic cancer and found that stages, treatments, CA19-9, and EphA2-NF were associated with a significantly poor prognosis of pancreatic cancer." (PMID 37712876, 2023). "This study demonstrated the clinical application of serum EphA2 as a biomarker for patients with early-stage pancreatic cancer using retrospective specimens." (PMID 37712876, 2023). "The AUCs for the diagnosis of pancreatic cancer (stages I/II/III/IV) using serum EphA2-NF, CA19-9, or EphA2-NF + CA19-9 (vs. test cohort HDs) in the validation cohort were 0.89, 0.89, and 0.97, respectively." (PMID 37712876, 2023). "We also showed by IHC in vivo that EphA2 cleavage occurs at the N-terminus of pancreatic cancer and IPMN with pancreatic cancer by IHC in vivo." (PMID 37712876, 2023). "The SD values for EphA2-NF in IPMN and PNET were small and tightly clustered around the mean, whereas the distribution of EphA2-NF values in pancreatic cancer cases was significantly wider than in patients with benign disease." (PMID 37712876, 2023). "The AUC values for pancreatic cancer diagnosis by serum EphA2-NF or CA19-9 (vs. HDs) were 0.99 and 0.93, respectively, suggesting that serum EphA2-NF was superior to CA19-9 for pancreatic cancer diagnosis." (PMID 37712876, 2023). "In this study, we used automated CLIA to show that the level of EphA2-NF, produced by the proteolytic cleavage of EphA2, was elevated in patient sera from early-stage pancreatic cancer and at pancreatic cancer development from IPMN." (PMID 37712876, 2023). "In contrast, the distribution of EphA2-NF values in patients with pancreatic cancer was significantly wider than that in patients with benign disease and HD." (PMID 37712876, 2023). "Using an nPES assay, they identified ephrin type-A receptor 2 (EphA2) as an EV marker for diagnosis of pancreatic cancer." (PMID 36770486, 2023). "For example, in pancreatic cancer and hepatocellular carcinoma, ligand-induced EphA2 signaling activates AKT signaling by enhancing its phosphorylation." (PMID 36835335, 2023). "A sandwich ELISA showed that serum EphA2-NF levels were significantly higher in most pancreatic cancers than in other cancers, suggesting its potential as a specific biomarker for pancreatic cancer." (PMID 37712876, 2023). "After confirming the prognosis, some EphA2-NF–high cases showed pancreatic cancer development and an increase in pancreatic duct size." (PMID 37712876, 2023). "Patients with pancreatic cancer in the validation cohort were classified into the serum EphA2-NF–high (≥50 pg/mL) and -low (<50 pg/mL) groups." (PMID 37712876, 2023). "The cut-off values for EphA2-NF were 50.0 and 74.0 pg/mL (based on the means ± SD for HD vs. pancreatic cancer and for HDs + IPMN vs. pancreatic cancer, respectively)." (PMID 37712876, 2023). "The mean values for the serum EphA2-NF level were 131.0 pg/mL for pancreatic cancer cases (n = 97), 68.2 pg/mL for IPMNs (n = 6), 65.5 pg/mL for PNETs (n = 66), and 36.0 pg/mL for HDs (n = 150)." (PMID 37712876, 2023). "To date, a variety of innovative biomarkers, including EphA2, have been developed for early-stage pancreatic cancer diagnosis." (PMID 37712876, 2023).